BNC1 (basonuclin zinc finger protein 1)
Description:
Transcriptional activator (By similarity). It is likely involved in the regulation of keratinocytes terminal differentiation in squamous epithelia and hair follicles. Required for the maintenance of spermatogenesis (By similarity). It is involved in the positive regulation of oocyte maturation, probably acting through the control of BMP15 levels and regulation of AKT signaling cascade. May also play a role in the early development of embryos (By similarity).
Synonyms: BNC; HsT19447; bn1; BSN1; POF16
Tractability: No criterion of Open Targets' tractability assessment is met for any kind of drug.
Gene: Protein-coding gene on chromosome 15 (83,255,884 to 83,284,664, reverse strand). Ensembl gene ENSG00000169594.
Subcellular location: Nucleus; Cytoplasm; Nucleus, nucleoplasm
Subcellular location (Human Protein Atlas): Nucleoplasm
Gene Ontology:
Molecular function: DNA-binding transcription activator activity; rDNA binding
Biological process: positive regulation of oocyte maturation; positive regulation of transcription by RNA polymerase I; epidermis development; positive regulation of cell population proliferation; regulation of transcription by RNA polymerase I
Cellular component: nucleoplasm; nucleus; nucleolus; cytoplasm; nuclear lumen
Genetic constraint (gnomAD): Loss-of-function variants: 8 observed, 68.06 expected, observed/expected ratio (o/e) 0.12, 90% interval 0.068 to 0.21. The upper end of that interval is the gene's LOEUF score, 0.21, which puts it in group 1 of 6, group 1 being the genes least tolerant of losing a copy. Missense variants: 1,068 observed, 1,290.2 expected, observed/expected ratio (o/e) 0.83, 90% interval 0.79 to 0.87. Synonymous variants: 449 observed, 471.85 expected, observed/expected ratio (o/e) 0.95, 90% interval 0.88 to 1.03.
Homologues: Orthologues: chimpanzee BNC1 (99% identical), macaque BNC1 (98% identical), pig BNC1 (88% identical), mouse Bnc1 (87% identical), rabbit BNC1 (87% identical), rat Bnc1 (86% identical), guinea pig BNC1 (86% identical), dog BNC1 (85% identical), tropical clawed frog bnc1 (59% identical), zebrafish BNC1 (45% identical), Drosophila melanogaster disco-r (20% identical), Drosophila melanogaster disco (11% identical), and 1 more. Paralogues in human: BNC2 (44% identical).
Diseases named in the same sentence as BNC1 in open-access papers:
BNC1 is named in the same sentence as 33 diseases in open-access papers, as found by Europe PMC text mining. Sharing a sentence is not in itself a finding about the gene and the disease. The quoted sentences say what the papers report.
pancreatic cancer (13 papers, 2016 to 2025). "SH3GL3 and BNC1 are both neither reported in the context of UF, however, SH3GL3 is reported as a colorectal cancer-associated gene, and BNC1 is reported to have association with pancreatic cancer." (PMID 31488892, 2020). "Conversely, BNC1 expression is downregulated in ovarian cancer and pancreatic cancer, suggesting a tumor suppressor function." (PMID 40444282, 2025). "The cfDNA methylation status of two pancreatic-cancer-associated genes, ADAMTS1 and BNC1, has been demonstrated to be highly sensitive and specific, enabling early pancreatic cancer diagnosis." (PMID 39200847, 2024). "The methylation status of ADAMTS1 and BNC1 in cfDNA shows promise for detecting pancreatic cancer during the early stages when curative resection of the tumor is still possible." (PMID 30953539, 2019). "Our studies identified two biomarkers ADAMTS1 (A disintegrin and metalloproteinase with thrombospondin motifs 1) and BNC1 (zinc finger protein basonuclin-1) as highly sensitive markers for the early detection of pancreatic cancer in tissue." (PMID 30953539, 2019). "We have recently identified promoter DNA methylation of the genes ADAMTS1 and BNC1 as potential blood biomarkers of pancreas cancer." (PMID 30953539, 2019). "Aberrant BNC1 silence induced by promoter hypermethylation has been reported in several types of human tumors, including pancreatic cancer, renal cell carcinoma, lung cancer, lymphocytic leukemia and the metastatic brain tumors." (PMID 26821013, 2016). "BNC1 has been shown to be silenced by promoter methylation in a wide variety of tumors, including pancreatic cancer, renal cell carcinoma, lung cancer, lymphocytic leukemia and the metastatic brain tumors originating from primary breast tumors." (PMID 26821013, 2016). "Over-expression of BNC1 in pancreatic cancer cell lines inhibited colony formation and cell proliferation in vitro." (PMID 26821013, 2016). "We found BNC1 to be hypermethylated in only 36% of pancreatic cancer patients with a specificity of 94%." (PMID 27891190, 2016). "Another study identified BNC1 and ADAMTS1 hypermethylation as potential biomarker to detect early‐stage pancreatic cancer, with sensitivities of 79% and 48% and specificities of 89% and 92%, respectively." (PMID 32243066, 2020). "When considering the combination panel of both genes (ADAMTS1 and/or BNC1), the combined panel was positive in 100% (8/8) of stage I, 88.9% (8/9) of stage IIA, 100% (20/20) of stage IIB, and 100% (2/2) of stages III and IV pancreatic cancers." (PMID 30953539, 2019). "The AUC for early stage, resectable pancreatic cancers was 0.91 (95% CI 0.85–0.95) for ADAMTS1, AUC 0.78 (95% CI 0.70–0.85) for BNC1 alone, while the AUC of the two-gene combination was 0.95 (95% CI 0.90–0.98)." (PMID 30953539, 2019). "Yi and colleagues used new methylation-on-bead technology with quantitative MSP to specifically screen serum circulating free DNA (cfDNA) for promoter methylation changes in the BNC1 and ADAMTS1 loci—two genes that were verified to be hypermethylated in pancreatic cancer." (PMID 34968245, 2021). "Similarly, BNC1 was positive in 62.5% (5/8) of stage I patients, 55.6% (5/9) of stage IIA, 65% (13/20) of stage IIB, and 100% (2/2) of stage III/IV pancreatic cancers." (PMID 30953539, 2019).
breast carcinoma (4 papers, 2015 to 2022). "In breast cancer cell and renal cell carcinoma lines, loss of BNC1 expression increases cell motility, which is associated with a poorer prognosis." (PMID 36198708, 2022). "One example was BNC1 (basonuclin 1), a downregulated zinc-finger transcription factor with numerous known targets, and loss of BNC1 increases the metastatic potential of breast cancer." (PMID 28225791, 2017). "The number of breast cancer cell that invaded following BNC1 knocked down was increased by 40 % (p = 0.006)." (PMID 26052355, 2015). "An in vitro screen that consisted of multiple rounds of breast cancer cell line injection into nude mice and reculturing of the resulting brain metastases showed that BNC1 was among a large number of genes overexpressed in mouse brain metastases." (PMID 26052355, 2015). "Forty-eight hours after initial transfection with siRNA oligos against BNC1, CCDC8 or GALNT9 breast cancer cell lines showed loss of specific gene expression." (PMID 26052355, 2015). "GALNT9, BNC1 and CCDC8 were knocked down in breast cancer cell lines by siRNA and applied to matrigel-coated invasion chambers as described in the methods." (PMID 26052355, 2015).
Infertility (4 papers, 2007 to 2025). "A mouse model carrying this mutation in Bnc1 demonstrated infertility, elevated FSH levels, decreased ovarian size, and reduced follicle count." (PMID 41393291, 2025). "The female mouse model with BNC1 frame-shift mutation showed infertility, due to the significantly increased serum follicle-stimulating hormone, and reduced ovary with a declined number of follicles." (PMID 35538402, 2022). "PCR detected Bnc1 −/− progeny, which were born at a reduced frequency (not shown) and the surviving pups developed normally except infertile." (PMID 17971852, 2007).
ovarian carcinoma (3 papers, 2020 to 2025). A malignant neoplasm originating from the surface ovarian epithelium. "The gamma-aminobutyric acid type B receptor subunit 2 (GABBR2) locus was discovered to pertain to combined phenotypes of UL and ovarian cancer, while the SH3 domain containing the GRB2-like 3/basonuclin zinc finger protein 1 (SH3GL3/BNC1) locus was associated solely with UL." (PMID 38790186, 2024). "However, only AOX1 of top five down-regulated genes was verified to be decreased in expression for expanding sample of ovarian cancers, with that of REEP1, BNC1, HAND2, and GSDME unchanged." (PMID 33135729, 2020).
breast tumors (2 papers, 2015 to 2017). "Our findings are consistent with this; we find that BNC1 is infrequently methylated in primary breast tumours (17 %) and frequently methylated and silenced in BBMs (73 %)." (PMID 26052355, 2015). "Both early and late methylation events will appear similarly in our initial analysis; the genes will be frequently methylated in BBM and infrequently methylated in unrelated primary breast tumours, this is the case for BNC1, CCDC8 and GALNT9." (PMID 26052355, 2015). "Consistent with this study, analysis of HumanMethylation 27 and 450 K array data from The Cancer Genome Atlas indicates that BNC1 Promoter methylation is an infrequent event in primary breast tumours." (PMID 26052355, 2015). "Of these, GALNT9 and BNC1 were infrequently methylated in primary breast tumors, suggesting that they may be metastasis virulence genes and dysregulation of these occur as late events involved in brain colonization of these cancer cells." (PMID 28993799, 2017). "CCDC8 was commonly methylated in brain metastases and their associated primary tumours whereas GALNT9 and BNC1 were methylated and silenced only in brain metastases, but not in the associated primary breast tumours from individual patients." (PMID 26052355, 2015). "However, frequent BNC1 promoter methylation (>60 %) in a small cohort of breast tumours has previously been reported." (PMID 26052355, 2015). "Our findings indicate that epigenetic dysregulation of GALNT9, CCDC8 or BNC1 in breast tumours may contribute to metastasis to the brain and possibly other distant organs." (PMID 26052355, 2015). "This analysis has identified three genes (BNC1, CCDC8 and GALNT9) that are differentially methylated in primary breast tumours and BBM." (PMID 26052355, 2015). "Promoter methylation of BNC1 (17 %) and CCDC8 (40 %) in primary breast tumours was infrequent (≤45 %), and statistically significantly lower than that of the frequency of methylation in BBM (p = 0.0001 and 0.01, respectively)." (PMID 26052355, 2015). "We have identified three genes, GALNT9, CCDC8 and BNC1, that were frequently methylated (55, 73 and 71 %, respectively) and silenced in BBM and infrequently methylated in primary breast tumours." (PMID 26052355, 2015). "From our broad-ranging screens, we have identified GALNT9, BNC1 and CCDC8 as frequently methylated in BBM and significantly less frequently methylated in primary breast tumours." (PMID 26052355, 2015). "GALNT9 and BNC1 methylation is uncommon in primary breast tumours and is often not detectable in the tumours that metastasise." (PMID 26052355, 2015). "GALNT9 and BNC1 promoter methylation and associated silencing is common in BBM but does not occur frequently in the originating breast tumours suggesting that their dysregulation may not necessarily benefit the primary tumour but are required for successful colonization of the brain." (PMID 26052355, 2015). "Our analysis of such tumour pairs identified that BNC1 and GALNT9 are not frequently methylated in any breast tumours, even those that will eventually develop into brain metastases where these genes are methylated." (PMID 26052355, 2015).
chronic pancreatitis (2 papers, 2019 to 2024). A chronic inflammatory process causing damage and fibrosis of the pancreatic parenchyma. "Using the combination panel (ADAMTS1 and/or BNC1), 87.5% (7/8) of chronic pancreatitis patients had positive methylation." (PMID 30953539, 2019). "Furthermore, the investigators found that LRFN5 and PXDN did not exhibit significant methylation frequency in patients with chronic pancreatitis (CP) compared to healthy individuals, providing better distinction than the panel of ADAMTS1 and BNC1 alone." (PMID 38672671, 2024).
liver cancer (2 papers, 2016 to 2017). An epithelial or non-epithelial malignant neoplasm that arises from the liver. "BNC1 is also a putative ESR1 target as ESR1 was bound in the proximal promoter of BNC1 in T-47D cell line, raising the possibility that BNC1 may also have a role for sexual dimorphism in liver cancer." (PMID 28673244, 2017). "Interestingly, BNC1 is also a putative ER receptor 1 (ESR1) target as ESR1 was bound in the proximal promoter of BNC1 in T-47D cell line (ENCODE data on UCSC genome browser), raising the possibility that BNC1 might also play a role in sexual dimorphism in liver cancer similar to FOXA1." (PMID 28673244, 2017). "The results showed that the hypermethylation of BNC1 did not correlate to patients’ age, tumor size, tumor number, portal vein invasion and Barcelona Clinic Liver Cancer (BCLC) stage." (PMID 26821013, 2016). "Unlike BNC1, the promoter region of BNC2 was seldom hypermethylated in both liver cancer cell lines and HCC tissues." (PMID 26821013, 2016).
pancreatic adenocarcinoma (2 papers, 2016 to 2017). "Hypermethylation of SFRP1, BNC1, and TFPI2 were in the univariate screening associated with poor survival for stage IV pancreatic adenocarcinoma." (PMID 29212200, 2017). "We developed a diagnostic prediction model (age >65, BMP3, RASSF1A, BNC1, MESTv2, TFPI2, APC, SFRP1 and SFRP2), which was able to differentiate between pancreatic adenocarcinoma and a large control group of great clinical relevance." (PMID 27891190, 2016). "A panel of hypermethylated genes (BMP3, RASSF1A, BNC1, MESTv2, TFPI2, APC, SFRP1 and SFRP2) are able to differentiate between patients with pancreatic adenocarcinoma and a most relevant control group." (PMID 27891190, 2016).
bladder squamous cell carcinoma (1 paper, 2025). A squamous cell carcinoma of the bladder arising from metaplastic epithelium. "BNC1 is markedly upregulated in bladder squamous cell carcinoma, implying an oncogenic role." (PMID 40444282, 2025).
brain tumours (1 paper, 2015). "Total RNA was extracted from 15 metastatic brain tumours to determine the expression of BNC1, CCDC8 and GALNT9 by RT-PCR." (PMID 26052355, 2015). "We analysed the methylation status BNC1, CCDC8 and GALNT9 in metastatic brain tumours and corresponding primary tumours from individual patients." (PMID 26052355, 2015).
cervical cancer (1 paper, 2023). A primary or metastatic malignant neoplasm involving the cervix. "Additionally, cervical cancer patients with elevated expression of BNC1, EHF, and IRF6 have a decreased rate of survival relative to patients with low expression of these genes." (PMID 37627195, 2023).
colon cancers (1 paper, 2014). "Tumor-specific BNC1 hypermethylation has been previously reported in RCC (46%) as well as in prostate, breast, lung and colon cancers." (PMID 24454902, 2014).
cyst (1 paper, 2023). A sac-like closed membranous structure that may be empty or contain fluid or amorphous material. "A combination of cyst features lesion size, CA19-9, and methylation status of BNC1/CACNA1G genes demonstrated an AUC of 0.92 (0.86–0.98)." (PMID 36803844, 2023).
esophageal squamous cell carcinoma (1 paper, 2025). Esophageal squamous cell carcinoma (ESCC) is a type of esophageal carcinoma (EC) that can affect any part of the esophagus, but is usually located in the upper or middle third. "Elevated levels of BNC1 expression have been reported in esophageal squamous cell carcinoma and basal cell carcinoma." (PMID 40444282, 2025). "Previous research has shown that BNC1 serves as a key transcriptional activator in esophageal squamous cell carcinoma and that LINC01305 recruits BNC1 to act on G-protein pathway suppressor 1 to promote tumor progression." (PMID 40444282, 2025).
gastric cancer (1 paper, 2025). A primary or metastatic malignant neoplasm involving the stomach. "Consequently, BNC1 may serve as a potential molecular marker for clinical diagnosis and is closely linked to the development and progression of gastric cancer." (PMID 40444282, 2025). "The IHC results showed that BNC1 was significantly downregulated in gastric cancer and that this downregulation correlated with advanced pathological stages and lymph node metastasis." (PMID 40444282, 2025). "Overexpression of BNC1 inhibited the proliferation, migration, and invasion of gastric cancer cells both in vitro and in vivo." (PMID 40444282, 2025). "In the current study, both in vivo and in vitro experiments confirmed that BNC1 acts as a tumor suppressor in gastric cancer cells." (PMID 40444282, 2025). "As a result, the role of BNC1 in gastric cancer was further investigated using more authentic gastric cancer cell lines, such as MKN-28 and AGS, to ensure more reliable and interpretable results." (PMID 40444282, 2025). "In conclusion, this study demonstrates that BNC1 inhibits the development and progression of gastric cancer cells by acting on the CCL20 promoter to mediate the JAK-STAT signaling pathway." (PMID 40444282, 2025). "This study established that BNC1 functions as a tumor suppressor in gastric cancer cells and negatively regulates its target gene, CCL20." (PMID 40444282, 2025). "In the current study, initial functional assays indicated that overexpression of BNC1 promotes apoptosis in gastric cancer cells." (PMID 40444282, 2025). "The initial functional assays from this study demonstrated that BNC1 overexpression promotes gastric cancer cell apoptosis." (PMID 40444282, 2025). "Given this classical mechanism, BNC1 may function in a similar manner to mediate its repressive effects in gastric cancer." (PMID 40444282, 2025). "The role of basonuclin 1 (BNC1), a zinc finger protein-specific transcription factor, in gastric cancer remains unclear." (PMID 40444282, 2025). "Elucidating whether BNC1 functions as an oncogene or tumor suppressor in gastric cancer could enhance our understanding of disease mechanisms and potentially lead to the development of targeted interventions." (PMID 40444282, 2025). "In summary, these findings suggest that BNC1 may regulate CCL20 expression in gastric cancer cells through direct binding to the CCL20 promoter region, inhibiting its transcriptional activity." (PMID 40444282, 2025). "In this study, BNC1 was downregulated in gastric cancer and functioned as a tumor suppressor." (PMID 40444282, 2025). "Low BNC1 expression correlates with advanced pathological stage and lymph node metastasis, while high CCL20 expression is associated with lymph node metastasis in gastric cancer patients." (PMID 40444282, 2025). "However, the role of BNC1 in gastric cancer remains poorly understood." (PMID 40444282, 2025). "This study identifies BNC1 as a novel tumor suppressor and proposes CCL20 as an oncogene in gastric cancer." (PMID 40444282, 2025). "Mechanistically, BNC1 suppresses CCL20 expression by binding to its promoter, leading to reduced activation of the JAK-STAT signaling pathway and promoting apoptosis in gastric cancer cells." (PMID 40444282, 2025). "Though transcription factors are known to regular gene transcription in various ways, the regulatory role of the transcriptional repressor BNC1 in gastric cancer has not been previously explored." (PMID 40444282, 2025). "Although these findings provide valuable insights, there are currently no reported studies investigating the role of BNC1 in gastric cancer." (PMID 40444282, 2025).
kidney cancer (1 paper, 2014). Primary or metastatic malignant neoplasm involving the kidney. "From this analysis 4 genes (FBN2, PCDH8, BNC1 and SFRP1) stand out as either particularly strong epigenetic biomarkers of kidney cancer or as significant predictors of patient outcome." (PMID 24454902, 2014).
lymph node metastasis (1 paper, 2025). "However, a significant relationship was observed between BNC1 expression and both lymph node metastasis and pathological stage." (PMID 40444282, 2025).